INS (insulin)
Diseases named in the same sentence as INS in open-access papers (continued):
Sharing a sentence is not in itself a finding about the gene and the disease.
diabetes (continued). "Diabetes is a serious chronic disease arising from insulin insufficiency, either as a result of peripheral insulin resistance, decreased insulin secretion or both." (PMID 36145121, 2022). "Increased BP was found to enlarge the level of markers of inflammation connected with the insulin signalling pathway and function of β cells, likely participating in the development of diabetes in this way." (PMID 35742943, 2022). "Signaling of such factors in target cells leads to impaired insulin signaling, diabetes, and metabolic syndrome establishment." (PMID 36432612, 2022). "In South Africa, initiating and managing insulin for people living with diabetes (PLWD), especially type 2, are major challenges considering the limited resources of the healthcare system, especially in primary care." (PMID 35924623, 2022). "Diabetes mellitus is a type of chronic metabolic disorder categorized by insufficiency in insulin activity and/or insulin secretion." (PMID 35282429, 2022). "Diabetes is a chronic condition that occurs when the organ responsible for insulin production (pancreas) stops making insulin or is unable to utilize the little it produces." (PMID 36359988, 2022). "Diabetes Mellitus is a metabolic disorder characterized by a chronic hyperglycemia due to an impaired insulin secretion and a decreased in peripheral insulin sensitivity." (PMID 37065173, 2022). "A microdevice that offers glucagon supplements in a safe, non‐invasive, and glucose‐responsive manner is ideal for avoiding fatal hypoglycemia consequences from insulin overdosage during daily diabetes treatment." (PMID 35957510, 2022). "Diabetes mellitus and obesity are interrelated, and studies claimed that insulin sensitivity is affected by body fat distribution." (PMID 35335362, 2022). "β-Cell dysfunction is a basic defect of diabetes, leading to insufficient basal insulin secretion and long-term poor control of postprandial hyperglycemia, leading to macrovascular lesions." (PMID 35509833, 2022). "The risk factors comprised age, duration of diabetes, eGFR, ACR, HDL-C, TG, variation in HbA1c and FPG, insulin use, diabetes retinopathy, and hypertension drug use." (PMID 35314714, 2022). "As a result, ΔCPR and duration of diabetes mellitus were considered independent factors in predicting withdrawal from insulin therapy." (PMID 35574023, 2022). "A recent study including 4678 participants from Malmö Diet and Cancer study identified a positive association between plasma furin levels and glucose, insulin, LDL-C, and BMI, as well as increased incidence of diabetes and mortality." (PMID 35399937, 2022). "ICI-induced diabetes is a rare but often permanent endocrinopathy requiring life-long insulin therapy." (PMID 35350573, 2022). "A recent study conducted during the pandemic period in the US has similarly reported higher uptake of telehealth (phone) consultations in patients with diabetes of older age and using insulin." (PMID 35640964, 2022). "In this study, participants who were insulin-deficient were more likely to be of the male gender, with a history of being admitted with ketosis and initiated on insulin therapy at the time of diagnosis of diabetes." (PMID 36992725, 2022). "Intriguingly, silencing of VMHCCKBR also ameliorates the hyperglycemia and weight loss in mice rendered diabetes induced by streptozotocin (STZ), despite similarly low insulin levels and β-cells mass." (PMID 35619170, 2022). "The predictors for a higher LDL-C trend were younger adults, Malay and Indian ethnicities, females, dyslipidemia, and diabetes treatment with lifestyle modification and insulin." (PMID 36317122, 2022). "NASH patients only develop diabetes when pancreatic beta cells are unable to increase insulin secretion to match the insulin resistance." (PMID 35203540, 2022). "Type 1 diabetes mellitus (T1D) is considered a T cell-mediated autoimmune disease, in which autoreactive T lymphocytes destroy the insulin-producing β cells in the pancreatic islets." (PMID 35741012, 2022).
diabetes (continued). "With escalating incidence of diabetes, synthetic insulin and antidiabetic agents are clinically administered for diabetic therapy, but these drugs present side effects, toxicity, and high costs." (PMID 36016679, 2022). "Diabetes patients usually need frequent insulin injections to maintain normal blood glucose levels, which is a painful administration manner." (PMID 35328783, 2022). "In children and adolescents, the management of diabetes is difficult due to various factors, including physiological factors such as changes in insulin resistance related to physical growth and puberty." (PMID 36568429, 2022). "The GQD and metformin groups represented similar insulin and glucagon co-expression pattern as the diabetes group." (PMID 35858880, 2022). "Insulin glycation is a key post-translational alteration in the pathogenesis of diabetes that can lead to long-term problems." (PMID 36295897, 2022). "Diabetes self-management aiming for strict glycemic targets requires insulin therapy (e.g., multiple daily injections or insulin pump therapy) and active participation from PWT1D, and sometimes of their relatives." (PMID 36401237, 2022). "is known as “insulin plant” because local communities use the infusions of various organs empirically to treat diabetes." (PMID 36558108, 2022). "The FDA refused to approve its use in combination with insulin for diabetes mellitus type 1 (T1DM), and phase III trials on SOTA in patients with T2DM and HF were regrettably and untimely terminated due to financial reasons and the COVID-19 pandemic." (PMID 35329796, 2022). "Diagnosis from Diabetes for >15 years was a statistically significant predictor of adherence to insulin therapy." (PMID 35704654, 2022). "Chronic diseases considered were chronic heart disease, chronic pulmonary disease (including asthma), diabetes treated with oral antidiabetics or insulin and neurological disorders." (PMID 35316288, 2022). "Finding insulin-secreting microorganisms and colonizing them in the gut would be a historic advance in the fight against diabetes." (PMID 36419554, 2022). "Researchers from the University of Alberta claim that insulin-producing cells developed from stem cells are secure for transplantation to wean diabetes patients from injectable insulin permanently." (PMID 36381916, 2022). "Compared to normal weight patients, obese patients were significantly younger (p = 0.043), and with insulin-dependent and non-insulin-dependent diabetes mellitus (p = 0.021 and p = 0.000)." (PMID 36538553, 2022). "This is not the case for Mg concentration, which is insensitive to changes in insulin sensitivity or hyperinsulinemia during pre-diabetes." (PMID 35768618, 2022). "Given to financial disparities between developed and emerging countries in the access to insulin, these patients are the ones who suffer the most from the severe chronic complications that diabetes entails." (PMID 36992760, 2022). "As expected, subjects with diabetes differed for all diabetes-related variables, except for insulin levels, and biochemical lipid parameters, when compared with healthy subjects." (PMID 36364703, 2022). "Type 1 diabetes mellitus (T1DM) is an autoimmune disease characterized by insufficient insulin production due to the destruction of the insulin-secreting β cells in the islets of Langerhans of the pancreas." (PMID 35745227, 2022). "We aimed to assess physical activity levels, and diabetes self-management practices in relation to exercise, among older adults with T1D using insulin pump therapy." (PMID 35233639, 2022). "Type 2 diabetes mellitus (T2D) is the result of a dysregulation of insulin production and signalling, leading to an increase in both glucose concentration and pro-inflammatory cytokines such as interleukin (IL)-6 and tumour necrosis factor (TNF)-α." (PMID 36463286, 2022).
diabetes (continued). "Lastly, a study using insulin resistant-HepG2 cell model, reported that spirulina protein had anti-diabetes effects in insulin resistant cell models, with 11 anti-diabetes peptides being identified, and LRSELAAWSR displaying the best activities on DPP-4." (PMID 36557218, 2022). "The four mortality modules relevant in both the general population and CKD were all a combination of proteins and metabolites and were related to diabetes / insulin secretion, cardiovascular disease and kidney function." (PMID 36329547, 2022). "Disease relevance of the insulin-reactive T cell clones was demonstrated by the capacity to efficiently transfer diabetes into NOD or NOD.scid neonatal (< 3 wks of age) recipient mice." (PMID 36032090, 2022). "One key factor in the progression of diabetes is reduced insulin sensitivity, which usually occurs in late adulthood." (PMID 36536359, 2022). "The prevalence of diabetes and early abnormal glucose metabolism in men is higher than that in women because insulin sensitivity differs between men and women." (PMID 35551654, 2022). "Conventional diabetes drugs exert their effects by promoting insulin secretion or improving insulin resistance." (PMID 35884961, 2022). "The observation that some m.3243A > G patients with MIDD present with diabetic ketoacidosis and/or require insulin from the time of diagnosis raised the possibility of an autoimmune process in the development of diabetes." (PMID 35552684, 2022). "These relationships persisted after adjustment for potential confounding factors including young person's sex and age, duration of diabetes and mode of insulin delivery." (PMID 36206303, 2022). "Some simple and cheap surrogate indices have been developed in human medicine to assess insulin sensitivity in patients with diabetes." (PMID 35326119, 2022). "This study also highlights the effects of Ramadan fasting in insulin-treated patients with diabetes, which results in major changes in glycemic profiles, particularly pronounced in the evening hours after the fast is broken." (PMID 35433783, 2022). "Since diabetes is a bihormonal disease that not only impaired insulin action but also elevated glucagon resulting in diabetic complication, the study reported that dysregulation of glucagon secretion has also been involved in the pathophysiology of T2DM." (PMID 35211170, 2022). "This review suggests that malnutrition at any postnatal age can have both acute and long-term adverse effects on pancreas function so that diabetes treatments should consider insulin production as well as insulin resistance." (PMID 35504844, 2022). "It was also confirmed that podocytes in the glomerular filtration barrier are insulin-sensitive cells, and insulin-specific antibodies have appeared on podocyte since the early stage of diabetes." (PMID 36072812, 2022). "PCPs had a significant increase in their confidence to manage insulin for individuals with diabetes, which was a commonly stated barrier before Project ECHO Diabetes was initiated in the clinics." (PMID 36589850, 2022). "The rapid development of diabetes technology over the past few decades includes continuous subcutaneous insulin infusion (CSII) as one of the most notable developments." (PMID 36422210, 2022). "In the present study, we aimed to evaluate the therapeutic effect of Passiflora edulis fruit peel aqueous (AFA) extract as an adjuvant to insulin to confer nephroprotection against streptozotocin-induced diabetes." (PMID 36266308, 2022). "In January 1922, Leonard Thompson, a 14-year-old boy, received his first injection of animal insulin and survived the complications of diabetes mellitus." (PMID 35890301, 2022). "Chronic low-grade inflammation has consistently been shown to precede the development of diabetes and atherothrombotic diseases, possibly due to its inhibitory effects on insulin signaling." (PMID 35757633, 2022).
diabetes (continued). "The patient then obtained progression-free survival with continuous sintilimab, although he experienced the new onset of ICI-induced diabetes after 24 cycles of sintilimab and required sustained insulin treatment." (PMID 36354692, 2022). "Our findings are in line with a study done in sub-Saharan Africa in which the major precipitants of DKA were new onset diabetes, missed insulin doses and infections." (PMID 35381004, 2022). "Only the endocrinologists/diabetes physicians (4, 40%) reported higher insulin usage under ‘others’ as a perceived barrier." (PMID 35960738, 2022). "While there are no definitive reports to suggest insulin analogues currently in clinical use promote higher cancer risk, controversial discussions surrounding the complex relationships between insulin therapy, diabetes and cancer continue." (PMID 35832429, 2022). "The current treatment of diabetes, which includes insulin therapy and avariety of allopathic medications, has been confirmed to have significant side effects and minimal effectiveness." (PMID 36518134, 2022). "Studies were selected if sedentary behaviour and physical activity were measured by accelerometer in the general population, and if associations were reported with glucose, insulin, HOMA-IR, insulin sensitivity, HbA1c, diabetes incidence, CRP and IL-6." (PMID 35544519, 2022). "People in intensive insulin therapy generally require advanced diabetes-specific numeracy skills and functional health literacy to interpret food labels and calculate insulin dosage based on current blood glucose levels and carbohydrate intake." (PMID 35682052, 2022). "On the other hand, GDM is considered similar to the T2DM type of diabetes in several aspects including inadequate insulin responsiveness and secretion." (PMID 35356248, 2022). "In contrast, a dangerous role is played in the liver and pancreas, where it stimulates hepatic gluconeogenesis and inhibits insulin secretion in response to glucose, stimulating diabetes onset." (PMID 35741464, 2022). "Another study showed that sharps disposal practices were worse in patients with diabetes who had been receiving insulin for more than a year than those who had been receiving it for less than a year." (PMID 36568796, 2022). "Genetic factors, obesity, inflammation, oxidative stress, hyperglycemia, hyperinsulinemia, cancer therapies, insulin and some oral hypoglycemic drugs appear to play a role in the crosstalk between diabetes mellitus and cancers." (PMID 35222270, 2022). "Type 2 diabetes mellitus is a metabolic disease characterized by hyperglycemia resulting from decreased insulin sensitivity and insulin secretion." (PMID 36204103, 2022). "Our current work provides a framework for designing alternative agonists comprised of nucleotides for IR, selectively potentiating insulin activity for diabetes treatment." (PMID 36310231, 2022). "We will first analyse ALA’s effects on insulin sensitivity and secretion, then discuss related diseases such as insulin resistance and diabetes." (PMID 36615676, 2022). "Patient III.4 is diagnosed with diabetes mellitus; therefore, he was prescribed insulin, as well as thyroxine tablets for hypothyroidism management." (PMID 35237542, 2022). "“You'll notice that they need to be on insulin, but they haven't been contacting the diabetes educators to report their levels” (F-dietitian—28 yrs)." (PMID 35782628, 2022). "An effect of this sort, for example, would be similar to what is observed in individuals with diabetes who have higher circulating levels of insulin due to lower insulin sensitivity." (PMID 36217192, 2022).
diabetes (continued). "Diabetes is characterized by the inability of the body to produce or respond to insulin, with the consequence that the body cannot control the level of sugar in the blood, namely glycemia." (PMID 35958117, 2022). "Diabetes is a chronic metabolic disease characterized by hyperglycemia resulting from disturbances in insulin secretion and effects." (PMID 35054072, 2022). "Diabetes mellitus is a chronic metabolic disorder characterized by high blood glucose levels resulting from impaired insulin production or response." (PMID 35501880, 2022). "Among the participants with diabetes, 53% (8/15) were prescribed insulin, 93% (14/15) were prescribed metformin, and 13% (2/15) were prescribed liraglutide." (PMID 35384850, 2022). "Our research found a substantial positive link between HBA1c, insulin hormone levels, and diabetes patients' age (r = 0.115, p-value = 0.037, r = 0.122, p-value = 0.027)." (PMID 39450303, 2022). "Seventy‐one children (52% males), with mean (SD) age of 12.2 ± 3.2 years with diabetes duration of 5.5 ± 3.6 years and on insulin pump therapy for 3.3 ± 3.1 years commenced HCL." (PMID 35642299, 2022). "When insulin production by the islets of Langerhans is depleted, the majority of type 2 diabetes mellitus patients become insulin-dependent." (PMID 36015105, 2022). "Phenylalanine stimulates the release of glucagon-like peptide-1 (GLP-1) and peptide tyrosine–tyrosine (PYY), decreases plasma ghrelin, stimulates the release of insulin, improves glucose tolerance in rats, and affects the development of diabetes." (PMID 35431942, 2022). "In diabetes mellitus (DM) treatment, Continuous Glucose Monitoring (CGM) linked with insulin delivery becomes the main strategy to improve therapeutic outcomes and quality of patients’ lives." (PMID 35528003, 2022). "Patients with diabetes mellitus type 2 (DM2) inhere impaired peripheral insulin action leading to higher perioperative morbidity and mortality rates, with hospital-acquired infections being one important complication." (PMID 34750659, 2022). "This study adds to this body of evidence on the accessibility and receptivity to using mHealth interventions among adults with T1D who use advanced diabetes technologies to monitor their glycemic control and manage insulin administration." (PMID 35749207, 2022). "TRPA1 channel agonists can treat obesity and other related diseases, such as type 2 diabetes, by regulating the secretion of insulin, providing a new avenue for study on the treatment of diabetes." (PMID 36313301, 2022). "Patients who are diabetic at the time of surgery or who have had an abnormal blood sugar level that was controlled on diet or insulin prior to surgery have a higher chance of diabetes getting worse after surgery." (PMID 35273837, 2022). "Type 2 diabetes mellitus (T2DM) is among the most common metabolic disorders and is mainly caused by defective insulin secretion by pancreatic β-cells and a loss of insulin sensitivity in target tissues." (PMID 36618710, 2022). "The metabolic disorder can be induced by high blood glucose levels or the insulin reduction in the diabetes patients." (PMID 35313683, 2022). "Diabetes is a chronic health condition that affects the metabolism of glucose in the body due to decreased insulin secretion from the pancreatic islets." (PMID 35336018, 2022). "The pancreatic beta-cells are a key factor in the development of diabetes because of their capability of secreting insulin which lowers the blood glucose level." (PMID 35742478, 2022). "Diabetes mellitus is a chronic condition marked by elevated blood glucose levels, which can result from either the death or dysfunction of the insulin-producing beta cells in the pancreas." (PMID 35769082, 2022). "Because hyperglycemia is a major feature of diabetes, efforts have focused on controlling depression by optimizing glucose management using insulin or glycemia-control agents." (PMID 36552776, 2022).